PVT1 (Pvt1 oncogene)
Diseases named in the same sentence as PVT1 in open-access papers (continued):
Sharing a sentence is not in itself a finding about the gene and the disease.
prostate carcinoma (63 papers, 2006 to 2026). A carcinoma that arises from epithelial cells of the prostate gland. "Silencing PVT1 using siRNA is associated with a significant decrease in survival and invasion of prostate cancer cells via preventing p38 phosphorylation." (PMID 35773731, 2022). "The long noncoding RNA, plasmacytoma variant translocation 1 (PVT1) at 8q24.21 plays an oncogenic role in prostate cancer, and has been implicated in prostate cancer invasion and metastasis." (PMID 33599076, 2021). "Long intergenic non-coding RNA (lincRNA) PVT1 is an overexpressed oncogene that is associated with AR in LNCaP prostate cancer cells, and with PRC2 in HeLa and many other types of cancer cells." (PMID 33430890, 2021). "An increased expression of PVT1 was observed when the risk allele of rs378854 at chromosome 8q24 is present in prostate tissue, thereby increasing the risk for prostate cancer." (PMID 32117705, 2020). "MiRNA-1207-3p, encoded by PVT1 is significantly under expressed in prostate cancer cell lines whereas apoptosis is induced in prostate cancer by the overexpression of this microRNA." (PMID 32117705, 2020). "Studies carried out have shown that the mechanisms underlying the regulation of PVT1 in prostate cancer vary considerably." (PMID 32117705, 2020). "A high PVT1 expression level in patients with prostate cancer has been shown to be associated with low overall survival." (PMID 31309249, 2019). "To investigate the biological roles of PVT1 and miR‐146a in prostate cancer, we applied gain‐of‐function and loss‐of‐function strategies." (PMID 27794184, 2016). "A functional variant (rs378854) in chromosomal region 8q24 that modulates PVT1 expression has been associated with prostate cancer." (PMID 23626673, 2013). "Here we present evidence that one of the 8q24 risk loci for prostate cancer is able to interact with the promoter of PVT1 and that the presence of the risk allele correlates with increased PVT1 gene expression in normal prostate tissue." (PMID 21814516, 2011). "In addition, high expression of LncRNA plasmacytoma variant translocation 1 (PVT1) made prostate cancer cells more proliferative, migratory and invasive, whereas LncRNA PVT1 knockdown led to the opposite phenotype." (PMID 37365581, 2023). "PVT1 could be used as a prognostic marker of prostate cancer as higher levels are associated with an advanced tumor stage and poor overall and disease-free rates of survival." (PMID 35741059, 2022). "This interaction involving rs16902359 in CASC11 and PVT1 plays a great role in SNP-SNP interactions and could be linked with the high risk of prostate cancer in men of African Ancestry (MoAA)." (PMID 32117705, 2020). "Furthermore, PVT1 is in a susceptibility locus for classical Hodgkin’s lymphoma and a SNP that causes increased PVT1 expression is associated with prostate cancer risk." (PMID 23887658, 2013). "Recently, PVT1 expression has been linked to SNP, rs378854, which is within the same haplotype block and in complete LD with rs620861, a prominent GWAS signal for prostate cancer." (PMID 23077621, 2012). "Chromatin confirmation capture experiments further showed that DNA regions surrounding rs378854 physically interacted with the PVT1 promoter, and suggested that predisposition to prostate cancer at 8q24.2 risk locus could be associated with PVT1 expression." (PMID 23077621, 2012). "There is some plausibility for this hypothesis based on examples of long-range interactions at chromosome 8q24, which influence gene expression, for example, an interaction between rs378854 (a SNP in linkage disequilibrium with rs620861, an established prostate cancer susceptibility SNP) and PVT1." (PMID 33374332, 2020). "This study investigates how PVT1 contributes to the prostate cancer phenotype under androgen stimulation." (PMID 41792045, 2026). "Knockdown of PVT1 was achieved using CRISPR-Cas13d in LNCaP prostate cancer cells subjected to androgen (R1881) or vehicle treatment." (PMID 41792045, 2026).
prostate carcinoma (continued). "PVT1 drives a genome-wide epigenetic reprogramming in prostate cells, underscoring the role of PVT1 as a positive regulator of oncogenic pathways in prostate cancer and highlighting PVT1's potential as a therapeutic target." (PMID 41792045, 2026). "Long non-coding RNA (lncRNA) plasmacytoma variant translocation 1 (PVT1) is involved in the occurrence and progress of prostate cancer." (PMID 36702978, 2023). "Knockout of PVT1 can significantly up-regulate expression of Caspase-3 in mouse prostate cancer tissue." (PMID 36702978, 2023). "We further expanded the cell density assay to DAOY (human medulloblastoma) and PC3 (human prostate cancer) cell lines and found an increase in PVT1 levels under low density in these non ovarian cell line models as well." (PMID 35820706, 2022). "In 2016, Liu and colleagues found upregulation of lncRNA PVT1 in prostate cancer; PVT1 promotes the development and progression of cancer by inducing methylation of the miR-146a promoter, thus inhibiting its expression." (PMID 35741059, 2022). "In conclusion, high PVT1 expression plays an important role in promoting tumorigenesis in castrate-resistant prostate cancer and PCa." (PMID 36195846, 2022). "By reducing miRNA-15a-5p expression, lncRNA PVT1 promotes KIF23 expression to prevent apoptosis in prostate cancer." (PMID 35773731, 2022). "For instance, the lncRNA PVT1 downregulated miR-146a by increasing the methylation level of the miR-146a gene to regulate tumor growth in prostate cancer." (PMID 35506202, 2022). "For instances, small nucleolar RNA host gene 1 (SNHG1) promotes cell proliferation, migration, and invasion in cervical cancer; Pvt1 oncogene (PVT1) predicts the prognosis of prostate cancer and regulates tumor growth." (PMID 35266446, 2022). "In prostate cancer, lncRNA PVT1 induces phosphorylation of p38 to promote both proliferation and invasion." (PMID 35773731, 2022). "We show that besides the known role of PVT1 on regulating miRNA levels, this lincRNA acted to repress the transcription of hundreds of mRNAs in prostate cancer cells." (PMID 33430890, 2021). "It (or its SNP) has been confirmed as a target miRNA of lnc-PVT1 in multiple diseases (prostate cancer, colon cancer)." (PMID 34947913, 2021). "Overall, we provide first evidence that PVT1 was involved in signaling a genome-wide androgen-dependent transcriptional repressive program of tumor suppressor protein-coding genes in prostate cancer cells." (PMID 33430890, 2021). "PVT1 exon 9 is overexpressed in prostate cancer and promotes tumorigenicity by increasing proliferation and migration." (PMID 33801373, 2021). "Knockdown of PVT1 in prostate cancer cell lines has been shown to increase the abundance of activated cleaved caspase-9 and -3 proteins and to induce cell apoptosis." (PMID 33430890, 2021). "PVT1 has recently been shown in prostate cancer cells to act as a sponge for microRNA-186, thus increasing the expression of Twist1 oncogene and promoting cell invasion and metastasis." (PMID 33430890, 2021). "In prostate cancer, PVT1 signals an androgen-dependent transcriptional repression program in prostate cancer cells and a set of the repressed genes predicts high-risk tumors." (PMID 34335862, 2021). "Nevertheless, PVT1 has also been described in prostate cancer to act in the nucleus to down-regulate miR-146a expression by inducing the methylation of CpG island in its promoter." (PMID 33430890, 2021). "To evaluate the relevance of PVT1 transcriptional repression in prostate cancer we analyzed RNA-seq data from 497 prostate adenocarcinoma samples (TCGA-PRAD)." (PMID 33430890, 2021). "Clinical studies demonstrate that increased PVT1 expression is correlated with shorter disease-free survival in prostate cancer and with shorter overall survival in renal cell and colorectal carcinoma." (PMID 33430890, 2021).
prostate carcinoma (continued). "Knockdown of PVT1 was shown to reduce prostate cancer growth in vitro and in vivo and increase cell apoptosis in prostate cancer cells." (PMID 34946977, 2021). "Although many studies have been carried out on the role of PVT1 in cancer, the specific roles of PVT1 transcripts in prostate cancer have been examined by very few groups." (PMID 32117705, 2020). "PVT1 knockdown significantly accelerated prostate cancer cells apoptosis and downregulated the expression of c-myc in an in vitro study." (PMID 32117705, 2020). "Here we show that the 8q24 prostate cancer rare variant, rs72725854 is present in an enhancer and regulates multiple lncRNAs genes namely, PCAT1, PRNCR1, PVT1, and proto-oncogene MYC in the region." (PMID 32680982, 2020). "The Ogunwobi laboratory also reported that PVT1 exon 9 is significantly overexpressed in prostate cancer cell lines derived from men of African Ancestry (MoAA)." (PMID 32117705, 2020). "Methylation of the miR-146a promoter induced by the overexpressed PVT1 resulted in the down-regulation of miR-146a and upregulation of PVT1 in prostate cancer." (PMID 32117705, 2020). "In a more recent study by the Ogunwobi laboratory, PVT1 exon 9 was found to be upregulated in prostate cancer tissues when compared to normal prostate tissues." (PMID 32117705, 2020). "Consistent with this pattern, PVT1 negatively regulates and reduces the expression of miR-186 as ceRNA in prostate cancer." (PMID 32117705, 2020). "This is consistent with previous studies on the expression of PVT1 exon 9 in prostate cancer cell lines." (PMID 32117705, 2020). "A possible mechanism for the oncogenic function of PVT1 exon 9 is by the regulation of PCNA (Proliferating Cell Nuclear Antigen) expression in prostate cancer." (PMID 32117705, 2020). "Data from many sources suggest that PVT1 is a major contributor to the development of prostate cancer." (PMID 32117705, 2020). "PVT1 has been previously reported to play an oncogenic role in the process of prostate cancer with the downregulation of microRNA-146a expression by PVT1 promoting the methylation of the CPG island in its promoter region." (PMID 31303891, 2019). "The standard curves were used to quantify the number of copies/μl of PVT1 exons 4A, and 4B, and 9 in different prostate cancer cell lines, human prostate tissue, human serum, mouse plasma, and human urine." (PMID 31877167, 2019). "Due to our focused research interest in PCa, we have decided to focus on PVT1 exons 4A, 4B, and 9 because of their potential role as biomarkers for prostate cancer (PCa)." (PMID 31877167, 2019). "PVT1 plays an oncogenic role in prostate cancer and knockdown of PVT1 inhibits prostate cancer growth both in vivo and in vitro and promotes cell apoptosis." (PMID 31877167, 2019). "Region surrounding rs378854 which is identified as a novel function prostate cancer-specific genetic variant interacts with the MYC and PVT1 promoters." (PMID 31760932, 2019). "The observed PVT1 exon 9-dependent tumors were invasive and expansile prostatic carcinomas with squamous metaplasia." (PMID 31766781, 2019). "PVT1 promotes prostate cancer invasion and metastasis by modulating epithelial to mesenchymal transition." (PMID 31877167, 2019). "In prostate cancer, PVT1 can act as a sponge for miRNA-186-5p and positively regulates Twist1 to promote EMT45." (PMID 30679629, 2019). "PVT1 expression is significantly correlated with tumor stage and can promote tumor cell proliferation, invasion, and metastasis in prostate cancer." (PMID 31309249, 2019). "And PVT1 has been demonstrated by multiple studies and research groups to be overexpressed in prostate cancer." (PMID 31877167, 2019). "Further, testing of human prostate tissue samples showed that the number of copies/μl of PVT1 exons 4A, 4B, and 9 is higher in prostate cancer samples in comparison to normal prostate tissues or benign prostatic hyperplasia tissues." (PMID 31877167, 2019).
prostate carcinoma (continued). "Downregulation of lncRNA PVT1 expression inhibits the proliferation, mobility and colony formation abilities of prostate cancer cells." (PMID 31877167, 2019). "For example, PVT1 knockdown significantly inhibited prostate cancer growth in vivo and in vitro and promoted cell apoptosis." (PMID 30008615, 2018). "In our previous study, we also demonstrated that PVT1 was overexpressed and played an oncogenic role in the progression of prostate cancer." (PMID 27794184, 2016). "But miR‐146a overexpression eliminated the effect of PVT1 knockdown on cell proliferation and apoptosis in prostate cancer cells." (PMID 27794184, 2016). "Taken together, these finding indicated that in prostate cancer, PVT1 regulated miR‐146a expression through inducing the methylation of CpG Island in its promoter." (PMID 27794184, 2016). "In this study, we aim to investigate the interaction between PVT1 and miR‐146a in prostate cancer and reveal the potential mechanism in prostate cancer carcinogenesis." (PMID 27794184, 2016). "The mRNA level of miR‐146a was significantly downregulated in prostate cancer tissues (P < 0.0001), whereas the PVT1 expression was obviously upregulated (P < 0.0001)." (PMID 27794184, 2016). "In contrast, PVT1 silencing markedly promoted miR‐146a expression in prostate cancer cells (P < 0.001)." (PMID 27794184, 2016). "Our study suggested a regulatory relationship between lncRNA PVT1 and miR‐146a in prostate cancer tumorigenesis." (PMID 27794184, 2016). "Our results showed that miR‐146a was downregulated and negatively correlated with PVT1 level in prostate cancer." (PMID 27794184, 2016). "In this study, we aim to explore the interaction between lncRNA PVT1 and miR‐146a in prostate cancer and reveal the potential mechanism in prostate cancer carcinogenesis." (PMID 27794184, 2016). "Our study suggested a regulatory relationship between lncRNA PVT1 and miR‐146a during the process of the prostate cancer tumorigenesis." (PMID 27794184, 2016). "PVT1 knockdown markedly promoted miR‐146a expression, whereas the expression of miR‐146a was significantly inhibited in prostate cancer cells transfected with PCDNA3‐PVT1." (PMID 27794184, 2016). "Due to the negative regulation relationship, the antitumor effect of PVT1 knockdown was counteracted when miR‐146a was silenced in prostate cancer cells." (PMID 27794184, 2016). "In our previous study, it has been found that PVT1 was overexpressed in prostate cancer and promoted prostate cancer growth in vivo and in vitro." (PMID 27794184, 2016). "The significant aberrant expression of miR‐146a in prostate cancer tissues and negative regulation relationship with PVT1 suggested possible biological significance in tumorigensis." (PMID 27794184, 2016). "In our previous study, we confirmed that PVT1 predicted patient prognosis and regulated tumor growth in prostate cancer." (PMID 27794184, 2016). "Our study first reported the regulatory relationship between PVT1 and miR‐146a in prostate cancer tumorigenesis." (PMID 27794184, 2016). "Linear regression analysis showed that the expression level of miR‐146a was negatively correlated with the PVT1 in prostate cancer (R2 = 0.7291, P < 0.0001)." (PMID 27794184, 2016). "And the antitumor effect of PVT1 knockdown was counteracted when miR‐146a was silenced in prostate cancer cells." (PMID 27794184, 2016). "Our previous study demonstrated that lncRNA PVT1 was overexpressed and played an oncogenic role in the progression of prostate cancer." (PMID 27794184, 2016). "Several nlincRNAs from a prostate cancer associated chromosomal locus, 8q24, are up-regulated in cancer along with other known prostate cancer associated genes including PCAT-1, PVT1, and PCAT-92." (PMID 25933431, 2015). "We sought to assess the expression of 12 annotated PVT1 exons in various prostate cancer cell lines." (PMID 26703666, 2015).
prostate carcinoma (continued). "The regions correspond to the oncogene Myc known to be over-expressed in prostate cancer along with the oncogene Pvt1, a Myc protein target which is over-expressed in transformed cells." (PMID 24937006, 2014). "Rs378854 variant reduces binding of the YY1 transcription factor, leading to increased expression of Pvt1 in prostate cancer cell lines while rs6983267 affects binding of the transcription factor TCF4 in CRC cells." (PMID 23240038, 2012). "LncRNA PVT1 serves as a ceRNA for miR-27b-3p to promote prostate cancer progression." (PMID 39951205, 2025). "PVT1 exon 9 overexpression is a newly uncovered aberration in prostate cancer (PCa)." (PMID 40024473, 2025). "Additionally, PVT1 expression is correlated with shorter overall survival of the patients with head and neck squamous cell carcinoma and prostate cancer." (PMID 36760720, 2023). "In conclusion, investigating the PVT1 locus could be very promising for a deeper understanding of prostate cancer development with potential therapeutic implications." (PMID 35090471, 2022). "Interestingly, Yang J. and colleagues reported that long non-coding PVT1 is involved in prostate cancer, since its expression is upregulated in the cancer tissues, and correlates also with poorer overall survival and disease-free survival." (PMID 35090471, 2022). "Exon 9 of the PVT1 gene was overexpressed in aggressive prostate cancer cases with African ancestry, suggesting this could be used as a biomarker for metastatic disease." (PMID 34946977, 2021). "Knockdown of PVT1 down-regulates the level of MYC protein in prostate cancer cell lines." (PMID 34940755, 2021). "lncRNA PVT1 can predict a prognosis in patients with prostate cancer and regulate the tumor growth." (PMID 33869042, 2021). "Furthermore, long non-coding RNA BLACAT1 inhibits cell proliferation in prostate cancer by acting on hsa-miR-361; long non-coding RNA PVT1 contributes to cell growth and metastasis in non-small-cell lung cancer by regulating miR-361-3p." (PMID 34948403, 2021). "Overall, these results suggest that increased levels of endogenous PVT1, known to occur in prostate cancer, could lead to downregulation of tumor suppressor genes and favor cell proliferation." (PMID 33430890, 2021). "Our group previously reported that PVT1 exon 9 was differentially expressed in prostate cancer." (PMID 33801373, 2021). "Knockdown of PVT1 in prostate cancer cells and in other types of cancer cells resulted in decreased cell viability, induction of apoptosis and reduction in tumor volume, however the mechanisms of action of PVT1 are largely unknown." (PMID 33430890, 2021). "In prostate cancer cells, we show a novel genome-wide androgen-related role of PVT1 lincRNA in signaling the transcriptional repression of protein-coding genes, and we show that the PVT1-targeted repressed gene set was enriched in tumor suppressor functions." (PMID 33430890, 2021). "More specifically, PVT1 exon 9 was overexpressed in prostate cancer tissue." (PMID 33801373, 2021). "Furthermore, PVT1 exon 9 expression was reported to be significantly higher in prostate cancer cell lines with an aggressive phenotype." (PMID 33801373, 2021). "In addition, the high PVT1 expressing prostate cancer patients also showed a higher Gleason score as compared to the subset of patients showing lower PVT1 expression." (PMID 32680982, 2020). "Notably, the morphologic appearance of the malignant neoplasms by PVT1 exon 9 overexpressing prostate epithelial cells was akin to prostatic carcinoma with squamous metaplasia." (PMID 31766781, 2019). "This assay may have non-invasive applications in prostate cancer and other diseases where PVT1 is dysregulated." (PMID 31877167, 2019). "Additionally, specific silencing of PVT1 exon 9 in the MDA PCa 2b prostate cancer cell line using a PVT1 exon 9 specific siRNA resulted in decreased PCNA expression." (PMID 31766781, 2019). "PVT1 plays an oncogenic role and regulates tumor growth in prostate cancer." (PMID 31877167, 2019).